APOE (apolipoprotein E)
Diseases named in the same sentence as APOE in open-access papers (continued):
Sharing a sentence is not in itself a finding about the gene and the disease.
Obesity (continued). "The present study examined whether the APOE ε4 allele was associated with working memory-related neural activity in sedentary midlife adults with overweight or obesity." (PMID 36504632, 2022). "One possible explanation for these effects on brain iron is that the APOE ε4 allele, obesity, insulin resistance and elevated blood lipid levels have been previously linked to an increased permeability of the blood-brain barrier, which is a possible cause for subsequent brain iron accumulation." (PMID 35951362, 2022). "Future larger studies are required to clarify whether these regions are particularly susceptible to obesity and APOE ε4 related tissue changes and why this may be." (PMID 35303671, 2022). "We showed that apoE-deficient rats present multiple organ damages (kidney, liver, lung and spleen) besides the known predisposition for obesity and affected lipid metabolism (two-fold increase in tissular damages in liver and one-fold increase in kidney, lung and spleen)." (PMID 34575848, 2021). "Next, we explored the association between APOE E4 and obesity in elderly schizophrenic patients." (PMID 34285334, 2021). "The comorbidity of obesity (metabolic syndrome and type II diabetes, cardiovascular disease, musculoskeletal disorders and cancer) coincide in part with disorders associated with variability of the APOE isoforms." (PMID 32646381, 2020). "Although Dgat1−/− and iDgat1−/− mice are resistant to diet-induced obesity, the absence of a comparable phenotype in Dgat1−/−ApoE−/− and iDgat1−/−ApoE−/− mice upon WTD feeding is likely the consequence of the resistance to diet-induced obesity caused by ApoE deficiency." (PMID 32882484, 2020). "APOE has been implicated in the development of diet‐induced obesity." (PMID 30462377, 2019). "Also, differences in HDL‐C remain significant only in individuals with obesity grade 2, both by alleles and by genotype of APOE." (PMID 31557780, 2019). "Therefore, these polymorphisms in the APOE gene influence both lipid profile and traits related to obesity." (PMID 30507998, 2018). "Such predisposing factors may include comorbidities; genetic variations, such as APOE ε4 allele expression and neprilysin polymorphism; and lifestyle factors, such as cognitive reserve, physical activity, obesity, alcohol, and smoking." (PMID 28678790, 2017). "Our data reveal a gene-environment interaction between APOE genotype and obesity, suggesting that APOE4 carriers may be more susceptible to obesity associated increases in AD risk." (PMID 28612048, 2017). "The association of APOE genotypes with plasma lipid disorders was tested by binary logistic regression analysis, taking into account the confounding factors of age, sex, residence, province and obesity-related traits." (PMID 27724906, 2016). "Furthermore, the effect of the APOE polymorphism on the lipid profiles has been reported to be modulated by obesity in children." (PMID 27724906, 2016). "We determined whether TSP1 deficiency protected mice from obesity associated insulin resistance in ApoE-/- mice." (PMID 25803585, 2015). "It is elaborated that deficiency of ApoE is more resistant to obesity in mice." (PMID 25148848, 2014). "However, it is also controversial about the relationship between ApoE polymorphism and obesity in different race." (PMID 25148848, 2014). "Associations between APOE isoforms and circulating lipid concentrations were described more than 30 years ago, and is also well known that these lipids are, in turn, associated with obesity." (PMID 25268647, 2014). "The sequence of the risk factors were (from the most influential to the least): education, age, number of children, marriage status, blood glucose, physical exercise, family structure, dysuria, coffee drinking, constipation, continuous sleeping time, ApoE allele, and obesity." (PMID 23210893, 2012).
Obesity (continued). "As BALB.apoE-/- mice, which are deficient in apoE, exhibited an increase in body weight, other mechanisms contributing to obesity may override the protective effect of apoE deficiency observed in our experiments." (PMID 22204493, 2011). "It seems that modulation of dietary cholesterol absorption, dietary cholesterol, obesity, sex and even hypolipidemic drug treatment may also be influenced by APOE polymorphism." (PMID 21244662, 2011). "This variant, near the APOC1 gene, have been reported to exist in LD with APOE ε2/ε3/ε4 polymorphisms, and it is unknown whether these associations are independent of the APOE alleles that are known to increase the risk of obesity." (PMID 37328602, 2024). "Therefore, the current inconsistent conclusions on the correlation between obesity and AD may be mainly due to APOE polymorphism, and different body fat distribution has little influence on it." (PMID 37686334, 2023). "Knowing that some APOE alleles are associated with obesity and that endocrine disorders are common in subjects with obesity, the present study aimed to explore associations between APOE polymorphism and endocrine functions in subjects with obesity undergoing bariatric surgery." (PMID 35205269, 2022). "Furthermore, it is also increasingly recognized that obesity may interact with genetic risk factors, notably APOE ε4." (PMID 35303671, 2022). "Among them, the epsilon 4 allele of the apolipoprotein E gene that encodes the major brain lipid carrier and metabolic disorders such as obesity and type 2 diabetes were identified as AD risk factors, suggesting that abnormal lipid metabolism could influence the progression of the disease." (PMID 32422896, 2020). "Besides, they were also sex-specific: only men showed these APOE allele associations with obesity." (PMID 32587511, 2020). "While APOE genotype and obesity independently affect AD risk, they may also have combined effects." (PMID 31554665, 2019). "Therefore, in the current study, we investigated whether TSP1 deficiency protects mice from obesity associated micro as well as macro-vascular complications in ApoE-/- mice." (PMID 25803585, 2015). "APOE (chromosome 19q12-13.2) is known to have a key role in determining inter-individual differences in lipid metabolism, and APOE gene variants may alter glucose metabolism moderated by obesity." (PMID 21283811, 2011). "The interactions between the FTO (Fat Mass and Obesity‐Associated Gene), TCF7L2 (Transcription Factor 7‐Like 2), and APOE (Apolipoprotein E) genes and nutrients play a crucial role in the metabolic pathways that determine disease risk." (PMID 41567168, 2026). "Several investigations have explored the metabolic and cognitive impacts of APOE genotypes and obesity separately." (PMID 40377430, 2025). "Apolipoprotein E (APOE) plays a tissue-specific role in diet-induced obesity: brain-expressed APOE promotes obesity, while hepatic APOE appears protective." (PMID 41354325, 2025). "We established an obesity model by feeding 6‐week‐old male ApoE−/− mice a high‐fat diet for 16 weeks." (PMID 40958408, 2025). "In this research, we studied the anti-obesity effects of butyrate in the high-fat diet-induced obese humanized APOE*3-Leiden.CETP mouse model." (PMID 40002674, 2025). "Even in apolipoprotein E (ApoE) KO mice subjected to HFD-induced obesity, calpain-1 is critical for inflammatory liver damage." (PMID 41294867, 2025). "With the exception of adiponectin, obesity-related biomarkers including glucose, insulin, triglycerides, cholesterol, and leptin were significantly aggravated in human APOE expressing mice compared to unmodified C57BL/6J mice." (PMID 37450924, 2024). "Many obesity models are resistant to atherosclerosis, whereas atherogenic apolipoprotein E KO mice fed a high-fat diet are less prone to develop diet-induced obesity, insulin resistance, and WAT inflammation than wild-type mice." (PMID 39143620, 2024).
Obesity (continued). "Protein-based subspecies of HDL, especially those containing apolipoprotein E (apoE) or apolipoprotein C3 (apoC3), offer a glimpse of a vast metabolic system related to atherogenicity, obesity, type 2 diabetes, and other diseases." (PMID 38438344, 2024). "Rikenella has been shown to increase its relative abundance from an exercise intervention conducted on ApoE knockout mice with additional net positive health changes such as decreased obesity." (PMID 39458548, 2024). "GFAP: Model 6 was again best fitting and showed faster average increases in those with Stage 3 kidney disease, higher average values in those with Stage 3 kidney disease, or higher APOE‐npscore and lower average values in men and people with obesity." (PMID 38970274, 2024). "In the current study, we seek to gain a greater understanding of the relationships among APOE genotype, obesity, and estrogen-based treatment in females." (PMID 39347015, 2024). "There were no statistical significances in the three-way interaction (p for APOE genotype × obesity × metabolic health status = 0.821)." (PMID 39210402, 2024). "Most of the measured obesity-related genes were altered in human APOE expressing mice, whereby the difference was greater and thus significant only comparing APOE3 with C57BL/6J mice." (PMID 37450924, 2024). "Certainly, the use of estrogen-based therapies is not without controversy, but a greater understanding of its risks and benefits is needed, especially in the contexts of APOE genotype and obesity." (PMID 39347015, 2024). "In conclusion, this study suggests that APOE genotype, obesity, and estrogen signaling interact to affect cognitive, metabolic, and lipid outcomes." (PMID 39347015, 2024). "The biological relevance of protein interactions was then investigated in 23 male APOE TR mice subjected to diet-induced obesity and DR." (PMID 36749362, 2023). "A previous study characterized that ApoE-/- mice are more resistant to becoming obese, and our work further highlights the complexity of ApoE in obesity-related chronic inflammation in adipose tissue." (PMID 38062308, 2023). "To explore and understand the correlation of ApoE with obesity progression, we first analyzed a database of human adipose tissues from obesity (GEO accession number GSE9624)." (PMID 38062308, 2023). "As expected, the expression of ApoE was also significantly reduced by over 40% in obesity of human OAT." (PMID 38062308, 2023). "Like in the observations in human subjects, QPCR also revealed the decrease of ApoE gene expression in adipose tissue from the HFD-induced obesity model and genetically obese (db/db) mice." (PMID 38062308, 2023). "Meanwhile, attention should be paid to obesity-related indicators of APOE ε3 carriers in the early stage, and they should regulate their body fat as early as possible and reduce the body fat mass to reduce the risk of AD." (PMID 37686334, 2023). "Due to the crucial part of the macrophage in obesity, we found that ApoE mRNA expression with a trend higher in obese and diabetic human subjects." (PMID 38062308, 2023). "Our findings support the synergic effect of obesity and APOE genotype on the development of T2D and AD." (PMID 37342358, 2023). "The signature of ApoE involved in inflammation and lipid metabolism is found both in mice and humans across multiple obesity models, suggesting the pluripotent role of ApoE in the NLRP3-mediated inflammation induced by obesity." (PMID 38062308, 2023). "Risks for AD, CVD, and T2D are all strongly increased by obesity, interactions that can be impacted by the APOE genotype." (PMID 36837905, 2023). "We uncovered a previously unknown role of ApoE in obesity as a crucial mediator connecting inflammation and overnutrition, which advances the understanding of the instigation of chronic inflammation during obesity and broadens the arsenal for obesity and associated metabolic disorders." (PMID 38062308, 2023).
Obesity (continued). "In another study the effect of quercetin on obesity with subjects who had various apolipoprotein E (APOE) genotypes were investigated." (PMID 36830032, 2023). "The apolipoprotein E-knockout (ApoE−/−) mice were used to develop the animal model of obesity by feeding high-fat diet." (PMID 35398040, 2022). "Thus, a reduction in 6-h circulating NEFA levels found in the current study may suggest less fat oxidation in subjects carrying the double risk alleles of the SNPs in APOC3 and APOE, which may increase risks of obesity as well as type 2 diabetes in these individuals." (PMID 36050800, 2022). "In conclusion, our findings demonstrate that in this mostly midlife age range of participants with overweight/obesity, we can detect significant differences in working memory-related brain activity as a function of APOE genotype." (PMID 36504632, 2022). "Central obesity was associated with reductions in myelin/neurite packing and size/complexity across all subfields, with APOE genotype modifying the effects of obesity on size/complexity." (PMID 35303671, 2022). "Animal studies have shown apoE knock out mice to be protected against obesity and suggested a differential effect of the APOE alleles on the ability of the body to store fat, with APOE3 mice having a higher body weight than APOE4 mice on a Western type diet." (PMID 36077164, 2022). "A 12-week exercise intervention in ApoE knockout mice that received a HFD significantly mitigated the induced obesity in terms of body weight gain, decrease of fat mass in body composition, and adipocyte morphology." (PMID 35172845, 2022). "The precise nature of these complex synergistic effects between obesity and APOE ε4 remain elusive and require further investigation." (PMID 35303671, 2022). "ApoE−/−/IKKε−/− mice were protected from diet-induced obesity but developed meta-inflammation in the adipose tissue, liver steatosis, and hypercholesterolemia and readily developed atherosclerotic plaques." (PMID 35662709, 2022). "These analyses controlled for the effects of age, sex and verbal intelligence, as we aimed to gain a better understanding of age and sex-independent effects of APOE, FH and obesity and their potential interactions." (PMID 35303671, 2022). "A recent animal study points to inflammation and neuronal plasticity mechanisms underpinning interaction effects between obesity and APOE genotype." (PMID 35303671, 2022). "The body weight of the WD groups (ApoE WD and ApoE WD EX) was significantly higher than that of the normal chow diet groups (WT CD and ApoE CD), but the exercise significantly ameliorated the WD-induced obesity (vs. ApoE WD)." (PMID 35256637, 2022). "Initial studies have identified genetic polymorphisms in IL-1 receptor antagonist, IL-15 receptor alpha, MTHFR, and apolipoprotein E as related to normal weight obesity." (PMID 36586433, 2022). "Another SNP for the formation of the APOE isoform, rs7412, is also well known for its effect on plasma lipid levels and obesity-related phenotypes, similar to rs429358." (PMID 36276968, 2022). "Instead, we primarily characterized the impact of the ε4 allele on working memory related brain activity among individuals with overweight/obesity by matching individuals on BMI across APOE genotype group." (PMID 36504632, 2022). "A previous analysis of data from the Framingham Offspring cohort also highlighted complex synergistic effects between APOE and obesity." (PMID 35303671, 2022). "The transplantation of ApoE−/−/IKKε+/+ bone marrow to ApoE−/−/IKKε−/− mice prevented double knockout mice from developing HFD-induced obesity, and the inflammasome and inflammatory response in the adipose tissue were reduced." (PMID 35662709, 2022). "The conventional conception has been that apolipoprotein E promotes obesity by the increase in lipid to white adipose tissue." (PMID 35205269, 2022).
Obesity (continued). "According to a cohort study of full-exome association of alanine aminotransferase, ApoE was found closely linked with fatty liver, and allele-specific variants of ApoE were associated with an increased incidence of MAFLD and obesity." (PMID 35720187, 2022). "Gene loci associated with coronary artery disease, including neurobeachin-like 1 (NBEAL1) and APOE, were upregulated in heart art ECs in obesity." (PMID 36400935, 2022). "Hsa-miR-1908-5p, which interacts with APOE in the tripartite network, is involved in the regulation of human obesity and cholesterol." (PMID 36092798, 2022). "While these results suggest potential anti-obesity actions of AR in females, these effects need to be further confirmed in animals with normal apoE functions." (PMID 33826123, 2022). "In a follow-up study, we further showed that global TSP-1 deletion abrogates lipid-filled lesion burden and VSMC abundance in ApoE–/– mice treated with recombinant leptin, at concentrations mimicking obesity." (PMID 36505365, 2022). "The degree of LFC had a positive correlation with total cholesterol, triglyceride, ApoB, and ApoE in patients with overweight/obesity and type 2 diabetes." (PMID 34899591, 2021). "The “weight loss” group also showed decreased levels of APOE, C5, CRP, LBP, NEGR1, and PRSS3, which have all been positively associated with obesity, inflammation, and metabolic disorders (22, –, 26)." (PMID 34519531, 2021). "Several potential obesity candidate genes and variants have been documented, including LEP and LEPR, which have been mainly implicated in monogenic obesity, as well as FTO, APOE, PPARG, and PPARA which have been mainly implicated in polygenic/common obesity." (PMID 34131278, 2021). "TREM2 is required for induction of monocyte-derived LAMs, in which LPL and APOE are induced by a TREM2-dependent mechanism as a consequence of HFD-induced obesity in mice." (PMID 34122343, 2021). "It was noticed that ApoE KO mice with defective lipid metabolism showed a preventive effect on obesity development." (PMID 34361033, 2021). "IKKε prevented obesity and inflammatory responses in the murine hearts of ApoE(-/-) and ApoE(-/-)/IKKε(-/-) mice that were fed an ND and HFD, respectively." (PMID 33628362, 2021). "In this context, we bred Cyp17a1-deficient mice on an atherogenic ApoE KO genetic background to study the role of this gene and a WTD on lipid metabolism and obesity." (PMID 34070975, 2021). "To examine how the different APOE genotypes respond to obesity, we used a diet induced obesity model." (PMID 31554665, 2019). "Our results suggest that APOE gene genotypes play an important role in the differential modulation of lipid profiles in the MA population with obesity." (PMID 31557780, 2019). "We then describe studies that have examined the effects of obesity and APOE genotypes together, with a focus on APOE4 and high fat diets." (PMID 30586872, 2018). "In our study, we investigated for the first time the effect of PYC on the browning of WAT by altering gene expression related to beige adipogenesis in ApoE-deficient mice, which provides new insight into the effect of PYC on obesity." (PMID 29577045, 2018). "As for ApoE, previous findings suggest that mice carrying the ApoE-3-genotype are more prone to develop impaired glucose tolerance leading to obesity and metabolic complications." (PMID 30302116, 2018). "In this study, we investigated the effects of PYC on obesity and WAT browning in apolipoprotein E- (ApoE-) deficient mice." (PMID 29577045, 2018). "Polymorphisms of the APOB, APOE, ADIPOQ, PLIN4, and HSD11β1 genes are important examples of genetic causes associated with dyslipidemias and obesity." (PMID 30507998, 2018). "Multiple studies have examined the metabolic and cognitive effects of APOE genotypes and obesity, but there are few studies linking the effects of HFD on both metabolism and cognition under the same conditions in terms of age and sex." (PMID 30586872, 2018).